RYK (receptor like tyrosine kinase)
Diseases named in the same sentence as RYK in open-access papers (continued):
Sharing a sentence is not in itself a finding about the gene and the disease.
cleft lip (2 papers, 2021 to 2025). Congenital defect in the upper lip where the maxillary prominence fails to merge with the merged medial nasal prominences. "Mutations in the RYK gene have been associated with craniofacial clefts in humans, although the exact role of the RYK gene and protein in cleft lip morphopathogenesis remain relatively unclear." (PMID 41226636, 2025). "The number of MSX2 and RYK gene-signal-containing cells was significantly increased in cleft lip tissue, probably due to WNT signaling disturbances and gene activation in cleft-affected tissue." (PMID 41226636, 2025). "Another finding was that the number RYK gene-signal-containing cells was increased in cleft lip tissue in comparison to controls." (PMID 41226636, 2025). "IHC findings showed decreased MSX1, NFκB p65, and CCL4 proteins in cleft lip connective tissue and endothelium, while RYK protein was decreased only in cleft connective tissue." (PMID 41226636, 2025). "Intriguingly, while the number of RYK gene-signal-containing cells was increased, the number of RYK protein-containing cells in cleft lip connective tissue and endothelium was decreased in comparison to controls." (PMID 41226636, 2025). "The number of MSX2 and RYK gene-signal-containing cells was significantly increased in the cleft lip in all three evaluated tissue types (epithelium, connective tissue, and endothelium) in comparison to the control group." (PMID 41226636, 2025). "The Mann–Whitney U test indicated a statistically significant difference for the number of RYK-positive epitheliocytes in the epithelium between the control group and the bilateral cleft lip affected tissue group (U = 3.0, p = 0.001)." (PMID 34684112, 2021). "Multiple statistically significant moderate correlations were found between PAX7, PAX9, and RYK within the unilateral cleft lip and isolated cleft palate affected tissue." (PMID 34684112, 2021). "For RYK, the median number of immunopositive cells within the epithelium of the unilateral cleft lip patient group was moderate to numerous (++/+++) and ranged from few to moderate (+/++) number to numerous to abundant (+++/++++) number of RYK-positive cells." (PMID 34684112, 2021). "Our study findings indicate that the RYK gene might be more functionally active in cleft lip tissue, possibly due to disturbed signaling pathways and tissue homeostasis characteristics, similarly to what is seen in the case of the MSX2 gene." (PMID 41226636, 2025). "The Kruskal–Wallis H test indicated a statistically significant difference for the number of RYK-positive structures in the epithelium between the controls, unilateral cleft lip group, bilateral cleft lip group, and isolated cleft palate group (H = 22.868, df = 3, p < 0.001)." (PMID 34684112, 2021). "Similarly, a strong correlation between PAX7-positive epitheliocytes in the epithelium and RYK-positive structures in the epithelium was found in isolated cleft palate affected tissue, but in unilateral cleft lip affected tissue this correlation was only moderate." (PMID 34684112, 2021). "Immunohistochemistry (IHC) for MSX1, RYK, NFκB p65, and CCL4 proteins and chromogenic in situ hybridization (CISH) for MSX2, RYK, and PTX3 genes were used to analyze postnatal human cleft lip tissue (15 patients) and control tissue (6 patients)." (PMID 41226636, 2025). "The information gathered in this study has provided additional insight about the presence and distribution of MSX1, RYK, NFκB p65, and CCL4 proteins and MSX2, RYK, and PTX3 genes in human cleft lip tissue." (PMID 41226636, 2025). "RYK protein immunoreactivity was significantly decreased only in cleft lip-affected connective tissue, possibly due to a disrupted WNT signaling pathway in cleft lip tissue." (PMID 41226636, 2025).
cleft lip (continued). "Why the significant decrease in RYK protein-positive cells was observed only in cleft lip connective tissue and not in the surface epithelium or endothelial cells remains uncertain, as RYK immunoreactivity was observed in all patient and control tissue samples in each of the localizations." (PMID 41226636, 2025). "In cleft lip patients, most statistically significant positive correlations involved the following factors: the PTX3 gene and NFκB p65 protein, then MSX1 protein-positive cells, RYK protein-positive cells, the CCL4 protein, the RYK gene, and then MSX2 gene-signal-containing cells." (PMID 41226636, 2025). "This might mean that cleft lip connective tissue postnatally is the most promising localization for further research to analyze disturbed WNT signaling, WNT ligands, RYK, and other WNT receptors in more detail, to clarify the exact morphopathogenetic mechanisms." (PMID 41226636, 2025). "This indicates that, although the presence of inflammation in the cleft lip patient group was not present, which would affect and increase the number of PTX3 gene-containing cells to significant levels, this factor still significantly correlated with the RYK and NFκB p65 proteins." (PMID 41226636, 2025).
mesothelioma (2 papers, 2022 to 2023). A usually malignant and aggressive neoplasm of the mesothelium which is often associated with exposure to asbestos. "By contrast, the phospho-RTK array data suggested that EGFR, RYK and EphA7 are activated upon progranulin stimulation of mesothelioma cells." (PMID 36471440, 2022). "Accordingly, our results demonstrate RYK action in modulating AKT activation in mesothelioma, as in fact RYK depletion inhibited basal and progranulin-dependent AKT activity." (PMID 36471440, 2022). "Taken together, these results suggest that progranulin might sustain the activation of multiple RTKs in mesothelioma cells and signaling triggered by progranulin to AKT and MAPK activation might rely on EGFR and RYK in mesothelioma cells." (PMID 36471440, 2022). "Since we have demonstrated that progranulin might activate EGFR and RYK in mesothelioma and considering that both EGFR and RYK might directly or indirectly modulate FAK activity, we asked whether progranulin-dependent regulation of FAK activity was mediated by EGFR and/or RYK." (PMID 36471440, 2022). "However, the role of RYK in mesothelioma cells remains unexplored." (PMID 36471440, 2022). "In mesothelioma, the WNT pathway controls cell proliferation, apoptosis and cisplatin-resistance and RYK phosphorylation was observed in 7 out of 12 diffuse malignant peritoneal mesothelioma frozen samples." (PMID 36471440, 2022). "It is tempting to hypothesize that, in mesothelioma, EGFR could be involved in progranulin-stimulated RYK tyrosine-phosphorylation and that progranulin signaling might depend on EGFR and RYK physical and functional interactions." (PMID 36980592, 2023). "In addition, because EGFR modulates EphA2 phosphorylation at Ser897 in mesothelioma cells, we can also hypothesize that EGFR could promote RYK phosphorylation indirectly by modulating EphA2 activity." (PMID 36980592, 2023). "Based on these published data, we can therefore speculate that the presence or absence of merlin in mesothelioma cells might determine different EGFR/RYK endocytosis/sorting, which could modulate the intensity of progranulin-dependent downstream signaling." (PMID 36471440, 2022). "Recently, we have demonstrated that in mesothelioma cells, EphA2 is not the major progranulin signaling receptor and progranulin action is instead mediated by EGFR and RYK, a co-receptor of the Wnt pathway." (PMID 36980592, 2023). "However, the contribution of EphA2 activation is not clearly defined in mesothelioma cells, where we identified by RTK arrays that progranulin promoted tyrosine-phosphorylation of EGFR and RYK." (PMID 36980592, 2023). "However, our results indicate that EphA2 is not the major functional receptor for progranulin in mesothelioma cells, where progranulin activates a complex signaling network including EGFR and RYK." (PMID 36471440, 2022).
osteosarcoma (2 papers, 2014 to 2018). A usually aggressive malignant bone-forming mesenchymal neoplasm, predominantly affecting adolescents and young adults. "RYK is a tyrosine receptor interacting with Wnt signalling which strongly contributes to the dialog between tumour cells and their stromal environment, especially in osteosarcoma." (PMID 24599309, 2014). "Finally, PDGFRα, Axl, PDGFRβ, RYK, EGFR, EphA2, EphA10 and IGF1-R are key targets of imatinib mesylate in osteosarcoma." (PMID 24599309, 2014).
acute leukemia (1 paper, 2020). A clonal (malignant) hematopoietic disorder with an acute onset, affecting the bone marrow and the peripheral blood. "In addition, high levels of RYK expression were found in acute leukemia cell lines and patient samples, and mutations in genes encoding several Wnt components, including RYK, were suggested to affect the pathogenesis of CLL." (PMID 32751131, 2020).
bone cancer (1 paper, 2022). A primary or metastatic malignant neoplasm affecting the bone or articular cartilage. "Wnt5b and the co-receptor RYK were upregulated in the sensory dorsal root ganglia of bone-tumor-bearing mice and therefore were assumed to participate in the transduction of pain due to bone cancer." (PMID 36497192, 2022).
breast tumors (1 paper, 2013). "Our IHC data, generated using RWD1 biotinylated specifically on N-glycan chains, demonstrates RYK expression on the stroma and cancer cells of human breast tumors." (PMID 24058687, 2013).
cleft palate (1 paper, 2021). Cleft palate is a fissure type embryopathy that affects the soft and hard palate to varying degrees. "Multiple statistically significant moderate correlations (rs = 0.4–0.6) were discovered between the number of PAX7, PAX9, and RYK-positive structures within the epithelium and connective tissue found in the isolated cleft palate affected tissue." (PMID 34684112, 2021).
colorectal cancer (1 paper, 2019). A primary or metastatic malignant neoplasm that affects the colon or rectum. "The study also identifies FZD6, RYK, and PTK7 as candidate receptors for Wnt-11 in colorectal cancer." (PMID 31261741, 2019).
endothelial dysfunction (1 paper, 2024). In vascular diseases, endothelial dysfunction is a systemic pathological state of the endothelium (the inner lining of blood vessels) and can be broadly defined as an imbalance between vasodilating and vasoconstricting substances produced by (or acting on) the endothelium. "Silencing of RYK reversed the Wnt5a-induced endothelial hyperpermeability, and thus revealed the role of Wnt5a/RYK signaling in endothelial dysfunction." (PMID 38397878, 2024).
frontotemporal lobar degeneration (1 paper, 2022). "In addition, GRN haploinsufficiency detectable in patients with frontotemporal lobar degeneration is associated with Wnt5a signaling in neuronal cells but no connection with RYK has been established." (PMID 36471440, 2022).
Hypocalcemia (1 paper, 2024). An abnormally decreased calcium concentration in the blood. "The RYK gene was previously associated with shortened long bones in the limbs in mice, while FGF23 was associated with subclinical hypocalcemia in dairy cows and 1,25-Dihydroxyvitamin D synthesis." (PMID 39512801, 2024).
laryngeal carcinoma (1 paper, 2019). Carcinoma that arises from the laryngeal epithelium. "The prognosis of laryngeal cancers could be improved by addition of markers such as IL1RAP, LANCL2, RYK, and SLC33A1." (PMID 31310629, 2019).
myeloma (1 paper, 2013). "We subsequently performed fusions of mouse splenocytes with myeloma cells after immunization with different recombinant versions of the human RYK extracellular region." (PMID 24058687, 2013).
neuroblastoma (1 paper, 2022). Neuroblastoma (NB) is the most common solid, extracranial childhood tumor. "One study demonstrated that RYK mRNA was detected across a panel of 25 neuroblastoma cell lines." (PMID 34716856, 2022). "Altogether, we found that RYK and ROR2, but not ROR1, are robustly associated with worse outcome in neuroblastoma." (PMID 34716856, 2022). "Together, these data suggest that the WNT modifying pseudokinases ROR2 and RYK represent potential novel therapeutic targets for neuroblastoma treatment and that current research on immuno-therapeutic strategies against ROR1 might need to be re-evaluated in favor of ROR2 and RYK." (PMID 34716856, 2022).
orofacial cleft (1 paper, 2021). A disorder of facial skeleton that is characterized by cleft lip and/or cleft palate that result in feeding, speech and hearing problems caused by failures during development. "Transcription factors paired box 7 and 9 (PAX7, PAX9) and receptor-like tyrosine kinase (RYK) have been previously associated with the formation of orofacial clefts but their exact possible involvement and interactions in the tissue of specific cleft types remains uncertain." (PMID 34684112, 2021).
ovarian tumor (1 paper, 2017). "RYK is involved with many signaling pathways in the neoplasia of ovarian tumor." (PMID 29108281, 2017).
pancreatic cancer (1 paper, 2021). "Specifically, we identified three RTKs, MET, EPHB6, and RYK, which are associated with a poor prognosis regardless of the immune status in patients with pancreatic cancer." (PMID 34479614, 2021).
rhabdomyosarcoma (1 paper, 2020). A rare aggressive malignant mesenchymal neoplasm arising from skeletal muscle. "Together, the antibody arrays and gene expression profiling identified a marked modulation of Wnt signaling during serial xenotransplantation and suggested RYK as a prospective target in rhabdomyosarcoma CSCs." (PMID 31941033, 2020). "This approach enabled us to identify several novel and promising rhabdomyosarcoma CSC-specific targets, e.g., ALDH6A1, SOX4, PAX3, CDH15, downregulated MIR145, or phosphorylated RYK, which warrant validation in subsequent mechanistic studies." (PMID 31941033, 2020).
sarcoma (1 paper, 2016). A usually aggressive malignant neoplasm of the soft tissue or bone. "Even though we were able to detect basal levels of expression and phosphorylation of RYK, an orphan atypical kinase related to RTKs, it is highly unlikely that it plays any significant role in driving sarcoma cell growth especially since it lacks any catalytic activity of its own." (PMID 26675259, 2016).
soft tissue sarcoma (1 paper, 2020). A malignant neoplasm arising from muscle tissue, adipose tissue, blood vessels, fibrous tissue, or other supportive tissues excluding the bones. "This is in agreement with our survival analysis on soft-tissue sarcomas demonstrating that upregulated expression of ALDH6A1 but not ALDH1A1 or ALDH3A1 significantly correlates with poor survival when combined with other genes identified in our model, i.e., CDH15, MYOD1, SOX4, ARMCX1, and RYK." (PMID 31941033, 2020).
Type 2 diabetes (1 paper, 2024). "miR-1271 caused the downregulation of both ALK and RYK, which were found to be in charge of the cytoskeleton structural degeneration in both AD and Type 2 diabetes mice." (PMID 38605867, 2024). "Anaplastic lymphoma kinase (ALK) and Receptor-Like Tyrosine Kinase (RYK), two non-canonical receptor tyrosine kinases (RTKs), have been shown to target miR-1271 in post-mortem AD and Type 2 diabetes tissues." (PMID 38605867, 2024).
cancer (16 papers, 2008 to 2023). A tumor composed of atypical neoplastic, often pleomorphic cells that invade other tissues. "Since receptor-like tyrosine kinase (RYK) activates the WNT/β-catenin pathway essential for cancer stem cell maintenance, we evaluated its contribution in conferring stemness to GBM cells." (PMID 28086236, 2017). "In addition, a role for RYK in mediating cell migration and anchorage-independent growth in cancer cells has been suggested." (PMID 36980592, 2023). "It would be interesting to investigate whether RYK might have a role in this context, and whether progranulin might either interfere or potentiate Wnt signaling pathways in cancer by functionally interacting with RYK." (PMID 36980592, 2023). "Multiple pathways associated with cancers such as pathways in cancer, PI3K-Akt signaling pathway, and Cytokine-cytokine receptor interaction, were observed to be enriched among LSCC patients with various expression of COPB2 and RYK." (PMID 35715770, 2022). "Moreover, to explore other cancer-promoting effects of RYK, we investigated whether it had an impact on anchorage-independent cell growth and on cell migration." (PMID 28086236, 2017). "Another important molecule affected by TNFα is the gene RYK receptor like tyrosine kinase (RYK) that like RTKs are deregulated in cancers and our revelation of the regulation of its gene expression by TNFα in HepG2 cells could provide information surrounding these phenomena." (PMID 20140224, 2010). "A functional cross-talk between WNT and FAK pathways has been previously reported in several cancer models, but there are no data supporting a role of RYK in this process." (PMID 36471440, 2022). "As observed in the case of tongue, genes associated with overall cohort, IL1RAP, ANO1, RYK, AP2M1, MFN1 and PSMD2 were significant prognosticators only in the late stage not in early cancers." (PMID 31310629, 2019). "Indeed, we found RYK dramatically upregulated in a large cohort of GBM samples and in GBM cancer stem cells either obtained directly from patients or derived from commercially available GBM cell lines." (PMID 28086236, 2017). "However, cancer type and MGMT methylation status were not significant risk factors, indicating that RYK expression remained as a potential independent prognostic factor in this patient group." (PMID 37242509, 2023).